PRL (prolactin)
Diseases named in the same sentence as PRL in open-access papers (continued):
Sharing a sentence is not in itself a finding about the gene and the disease.
anencephaly (1 paper, 2025). A rare neural tube defect during pregnancy, resulting in the absence of a large portion of the brain and skull in the fetus. "Low PRL levels correlate with anencephaly, while high maternal serum PRL levels are linked to growth retardation and anencephaly." (PMID 40078368, 2025). "Notably, altered PRL levels have been observed in conditions such as preeclampsia, anencephaly, and intrauterine growth restriction, all of which coincide with critical periods of neuronal migration, synaptogenesis and gliogenesis during fetal brain development." (PMID 40078368, 2025).
anxiety depression (1 paper, 2024). "At the same time, ZZCD could affect and participate in the process of neuroactive ligand/receptor interaction, regulate the HPA axis and secretion of prolactin and estrogen, and interfere with MAPK and TNF signaling pathways to reduce the level of inflammation to treat anxiety depression." (PMID 37905694, 2024).
bone metabolism disorder (1 paper, 2022). "Clinical and animal experiments have proved that abnormal prolactin level is related to bone metabolism disorder." (PMID 36590764, 2022).
bone tumors (1 paper, 2016). "Therefore, although the prolactin pathway is active in both SSM2 and SSM3 bone tumors, PrlR signaling is not sufficient to mediate the growth of ERα+/PR+ SSM3 cells in bones in the absence of ovarian hormones." (PMID 27391074, 2016).
chondrosarcoma (1 paper, 2022). A malignant cartilaginous matrix-producing mesenchymal neoplasm arising from the bone and soft tissue. "The cell line OUMS-27, derived from chondrosarcoma tumor, could show a significantly higher proliferative effect of PRL in comparison to the non-stimulated group in the 72 h study." (PMID 35406699, 2022).
colon adenocarcinoma (1 paper, 2024). "Lastly, PRL shows high expression linked to risks in colon adenocarcinoma (COAD) and BRCA, yet has favorable effects for KIRC, showcasing the diverse roles this gene plays in tumor biology." (PMID 39635438, 2024).
complex partial seizures (1 paper, 2024). "For the differentiation of ESs from PNESs, several studies have shown that elevated serum prolactin may be highly predictive of either generalized tonic–clonic or complex partial seizures." (PMID 39000494, 2024). "Notably, after complex partial seizures or generalized tonic–clonic seizures, serum prolactin transiently augments in approximately 60% of cases, while interictal epileptic discharges from the temporal lobe may induce long-term modifications of the hormone release." (PMID 39000494, 2024).
Corynebacterium infection (1 paper, 2023). "Corynebacterium infection can also be a predictor of GM, especially in patients with high prolactin levels or a history of recent lactation." (PMID 37138612, 2023).
delirium tremens (1 paper, 2022). "In addition, AUD-related factors including longer duration of drinking, history of delirium tremens, greater severity of AUD and lower levels of prolactin were associated with suicide attempt in males." (PMID 35848151, 2022). "In addition, AUD-related variables including longer duration of drinking, history of delirium tremens, more severe AUD and lower levels of serum prolactin were associated with suicide attempt in male AUD patients." (PMID 35848151, 2022).
demyelination (1 paper, 2024). "Similarly, PRL increases the production of cells that produce anti-MOG antibodies that induce demyelination and correlates with the serum level of PRL in patients with MS." (PMID 38680484, 2024).
DHPR deficiency (1 paper, 2025). "Patients with PTPS deficiency had higher prolactin levels compared to patients with DHPR deficiency." (PMID 39835220, 2025). "As we found here, Prolactin levels are more pronounced in patients with PTPS deficiency than in patients with DHPR deficiency, which can also be used to monitor the treatment, with normal values indicating adequate L‐dopa replacement." (PMID 39835220, 2025).
dilated cardiomyopathy (1 paper, 2023). Cardiomyopathy which is characterized by dilation and contractile dysfunction of the left and right ventricles. "Downregulated genes targeted by upregulated miRNAs were significantly enriched in dilated cardiomyopathy, adrenergic signaling, and prolactin signaling pathways in hypothalamic tissue." (PMID 37943864, 2023).
Down syndrome (1 paper, 2017). "Interestingly, PRL cell auto-abs were also found in patients affected by neurological diseases (Alzheimer’s and Down’s syndrome)." (PMID 29099758, 2017). "However, when the same study was repeated by another group, only 2 out of the 23 sera from patients affected by Alzheimer or Down’s syndrome, revealed APAs against PRL cells." (PMID 29099758, 2017).
encephalitis (1 paper, 2025). An acute inflammatory process affecting the brain parenchyma. "PRL may emerge as a dual‐edged modulator in anti‐NMDAR encephalitis, its therapeutic targeting requires careful consideration of context‐dependent effects." (PMID 41163354, 2025). "We categorized patients with anti‐NMDAR encephalitis into Normal PRL and High PRL groups based on whether serum PRL levels fell within the normal reference range (defined as < 557.1 mIU/L for females and < 407.4 mIU/L for males)." (PMID 41163354, 2025).
endometrial adenocarcinoma (1 paper, 2022). "Additionally, over-expression of PRL in the Ishikawa endometrial adenocarcinoma cell line increases cyclin D1 (CCND1) mRNA levels and enhances cell cycle progression." (PMID 35773139, 2022).
epithelial tumours of the ovary (1 paper, 1986). "An immunoperoxidase technique has been utilised for the demonstration of follicle stimulating hormone (FSH), luteinising hormone (LH) and prolactin (PRL) binding sites in normal human ovaries and in a wide range of benign and malignant epithelial tumours of the ovary." (PMID 3083857, 1986).
esophagitis (1 paper, 2025). An acute or chronic inflammatory disease affecting the esophageal wall. "Reduced severity of esophagitis was associated with downregulation of EGF, IL-16, CCL3, CCL7, and prolactin, suggesting decreased inflammation." (PMID 39808500, 2025).
fibrosarcoma (1 paper, 2026). A malignant mesenchymal fibroblastic neoplasm affecting the soft tissue and bone. "Functionally, PRL not only enhanced liposarcoma cell and fibrosarcoma cell proliferation but also conferred resistance to MDM2 inhibitors." (PMID 42083506, 2026).
focal epilepsy (1 paper, 2025). A seizure caused by a localized disorder. "Elevated PRL concentrations have been observed after both electroconvulsive therapy and spontaneous seizures and studies have consistently shown that PRL levels are higher in individuals with focal epilepsy compared to their healthy counterparts." (PMID 41323226, 2025).
Follicular Cyst (1 paper, 2025). Cyst due to the occlusion of the duct of a follicle or small gland. "In many of the previously reported cases, relatively elevated baseline LH levels, slightly elevated PRL levels, and spontaneously occurring follicular cysts were observed." (PMID 40725685, 2025).
functional dyspepsia (1 paper, 2023). "We found increased prolactin levels from day 0 to day 28 after treatment with domperidone in functional dyspepsia patients, specifically in males aged less than 40 years, who are married and belong to middle socioeconomic status." (PMID 38249246, 2023). "We found increased prolactin levels from day '0' to day '28' after treatment with domperidone in functional dyspepsia patients, specifically in male participants aged less than 40 years, who are married and belong to middle socioeconomic status." (PMID 38249246, 2023). "Thus, to explore this intriguing link between domperidone and prolactin, the present study was undertaken by investigating the effect of 30 mg domperidone therapy (for 28 days) on prolactinemia in functional dyspepsia patients." (PMID 38249246, 2023).
fungal infection (1 paper, 2014). "It has been also found that anterior pituitary cells recognize and respond to fungal cell wall glucans by appropriately stimulating the secretion of prolactin, a hormone that plays an important role in the response to fungal infection." (PMID 25243181, 2014).
generalized tonic clonic seizures (1 paper, 2024). "It is also worth noting that the serum prolactin level was normal on admission, as this helps aid us in considering alternate causes of the elevated CK than seizures as elevated prolactin has been associated with generalized tonic clonic seizures." (PMID 39346748, 2024).
hematoma (1 paper, 2022). A hematoma is a collection of blood from a vascular structure into an extravascular space. "Among the hormones, lower PRL level was correlated with higher tumor volume (r = −0.5114, p = 0.030), while the higher level of cortisol 8AM was correlated with higher hematoma volume (r = 0.5155, p = 0.029)." (PMID 35360427, 2022). "Moreover, prolactin (PRL) and cortisol 8AM were found to be correlated with the volume of the tumor and the hematoma, respectively." (PMID 35360427, 2022). "Moreover, a negative correlation between PRL and the tumor volume and a positive correlation between cortisol 8AM and the hematoma volume were found." (PMID 35360427, 2022).
Hepatomegaly (1 paper, 2024). Abnormally increased size of the liver. "Hepatomegaly was identified in 28 patients (18.7%), with 15 patients (53.6%) having normal prolactin levels and 13 patients (46.4%) with increased levels (p=0.458)." (PMID 39650982, 2024).
hepatopulmonary syndrome (1 paper, 2025). Hepatopulmonary syndrome (HPS) is a lung disease characterized by widening of arteries and veins (dilatation) in the lungs in people who have chronic liver disease. "Second, the relationship between serum prolactin levels and complications such as spontaneous bacterial peritonitis and hepatopulmonary syndrome could not be evaluated due to the small number of cases with these conditions." (PMID 39925608, 2025).
hyperestrogenism (1 paper, 2025). Abnormally high level of estrogen. "Therefore, women with PCOS are also characterized by relative hyperestrogenism, which in turn may explain higher PRL levels in these individuals." (PMID 39153031, 2025).
Hyperphenylalaninemia (1 paper, 2016). "Since dopamine biosynthesis begins from tyrosine, and its intracerebral availability depends on phenylalanine metabolism, it was hypothesized that prolactin secretion might be altered by the hyperphenylalaninemia observed in PKU." (PMID 27169416, 2016).
hypothalamic disorder (1 paper, 2022). Neoplastic, inflammatory, infectious, and other diseases of the hypothalamus. "The increase of serum PRL level can be found in patients with non-PRL-secreting tumors due to hypothalamic disorders." (PMID 35360427, 2022).
Hypoxemia (1 paper, 2010). An abnormally low level of blood oxygen. "Hypoxemia and chronic sleep fragmentation could affect the sleep-entrained prolactin (PRL) rhythm." (PMID 20182553, 2010).
idiopathic hypersomnia (1 paper, 2021). Idiopathic hypersomnia is a sleep disorder classified in two forms: idiopathic hypersomnia with long sleep time and idiopathic hypersomnia without long sleep time. "The evaluation of EDS by means of objective vigilance tests, in particular MSLT, would help identifying subjects with objectively assessed EDS who could be diagnosed as idiopathic hypersomnia and to establish if increased PRL may be a common finding in this diagnostic category or not." (PMID 34942875, 2021).
imbalance (1 paper, 2025). "Meantime, the consistent inverse relationship between PRL concentrations and lymphocyte proportions across treatment phases suggests PRL is associated with immune imbalance." (PMID 40948778, 2025).
in situ breast cancer (1 paper, 2015). "The association between prolactin and in situ breast cancer risk, however, has received less attention." (PMID 25887963, 2015). "We found a significant positive association between higher circulating prolactin levels and risk of in situ breast cancer among all women [pre-and postmenopausal combined, ORlog2 = 1.35 (95% CI 1.04-1.76), Ptrend = 0.03]." (PMID 25887963, 2015). "The relationship between prolactin and in situ breast cancer risk was confined to tumors diagnosed within the first 4 years from blood donation." (PMID 25887963, 2015). "In this prospective study, we observed a significant positive association between pre-diagnostic circulating prolactin levels and risk of in situ breast cancer." (PMID 25887963, 2015). "We analysed the relationship between pre-diagnostic prolactin levels and the risk of in situ breast cancer overall, and by menopausal status and use of postmenopausal hormone therapy (HT) at blood donation." (PMID 25887963, 2015). "Our study shows that higher circulating levels of prolactin may be associated with increased risk of in situ breast cancer." (PMID 25887963, 2015). "In the current study, prolactin was associated with in situ breast cancer among postmenopausal nulliparous women but not in parous women." (PMID 25887963, 2015).
inner ear disorder (1 paper, 2026). A non-neoplastic or neoplastic disorder affecting the inner ear. "In a comparative study on stress hormones across inner ear disorders, Horner and Cazals found that MD patients showed altered stress-hormone regulation, including a distinctive positive correlation between cortisol and prolactin in females, a pattern absent in males and in other inner ear disorders." (PMID 41594173, 2026).
interstitial lung disease (1 paper, 2025). A diverse group of lung diseases that affect the lung parenchyma. "Although these agents are generally well tolerated and effective in reducing prolactin levels and often tumor size, they have been implicated in rare but serious fibrotic complications, including interstitial lung disease (ILD)." (PMID 40236612, 2025).
Intraventricular hemorrhage (1 paper, 2018). Bleeding into the ventricles of the brain. "When the cutoff value of 80 was used, preterm neonates delivered to mothers with PRL ≥80 showed significantly poor outcomes in APGAR score, RDS, intraventricular hemorrhage, and perinatal death." (PMID 30693142, 2018).
invasive lobular carcinoma (1 paper, 2010). "In this population, we did identify a stronger relationship between high PRL levels and postmenopausal invasive lobular carcinoma." (PMID 20736944, 2010). "Our finding of the association of higher PRL levels with invasive lobular carcinoma was independent of HRT use." (PMID 20736944, 2010).
ischemia reperfusion injury (1 paper, 2020). Adverse functional, metabolic, or structural changes in ischemic tissues resulting from the restoration of blood flow to the tissue (reperfusion), including swelling; hemorrhage; necrosis; and damage from free radicals. "The synergistic effect of trophic factors in combination with MEL, PRL, TSH, ACTH and PGE1 may increase their effectiveness in the prevention and therapy of ischemia-reperfusion injury." (PMID 32392782, 2020).
latent infections (1 paper, 2025). "This process, characterized by increased cortisol and prolactin levels and a rapid decline in estrogen and progesterone, could exacerbate dormant autoimmune conditions or trigger latent infections, making this period especially vulnerable to immune-related complications." (PMID 40567348, 2025).
Leber congenital amaurosis (1 paper, 2024). Leber congenital amaurosis (LCA) is a retinal dystrophy defined by blindness and responses to electrophysiological stimulation (Ganzfeld electroretinogram (ERG)) below threshold, associated with severe visual impairment within the first year of life. "We now show that this shorter PRL transcript is also expressed in RPGR-XLPRA1 (X-Linked Progressive Retinal Atrophy 1, caused by a five-nucleotide deletion in the RPGR exon ORF15) and NPHP5-LCA (Leber Congenital Amaurosis, caused by a single nucleotide insertion in exon 10 of the IQCB1/NPHP5 gene)." (PMID 39294136, 2024).
leukodystrophy (1 paper, 2021). Leukodystrophies are a group of rare, progressive, metabolic, genetic diseases that affect the brain, spinal cord and often the peripheral nerves. "A high percentage (41%) of patients with 4H leukodystrophy were found to have abnormal prolactin levels, where variability was seen in elevated (18%), or deficient (23%) levels." (PMID 33005949, 2021). "Limited information is available on the typical prolactin levels in patients with 4H leukodystrophy; 2 case reports have previously reported low prolactin levels in 2 patients, who were also included in this study." (PMID 33005949, 2021).
lichen planus (1 paper, 2021). A chronic, recurrent, pruritic inflammatory disorder of unknown etiology that affects the skin and mucus membranes. "In this cross-sectional case control study, the serum level of LH, FSH, and prolactin of 40 women with lichen planus who have been referred to Shiraz Dental Faculty, Oral and Maxillofacial Disease Department during 2018-2019 has been evaluated in comparison to 40 healthy controls." (PMID 34746311, 2021).
malaise (1 paper, 2019). A feeling of general discomfort or uneasiness, an out-of-sorts feeling. "AEs with an incidence of 10% or higher were malaise (12.3%), constipation (11.7%), blood prolactin increased (11.7%), akathisia (11.7%), and weight increased (10.6%)." (PMID 31242884, 2019).
malignant prolactinoma (1 paper, 2023). "For patients with malignant prolactinoma, temozolomide is another medication to reduce prolactin levels." (PMID 37143698, 2023).
mental retardation (1 paper, 2023). "For example, people with mental retardation were found to have increased blood pressure and heart rate after surgery, as well as significantly higher levels of cortisol and prolactin." (PMID 37878069, 2023).
metastatic cancer (1 paper, 2021). A carcinoma which has spread from the original site of growth to another anatomic site. "PRL expression levels are greatly increased in metastatic cancer and regenerating liver cells, but nothing is known about the signals that control PRL phosphorylation and oxidation." (PMID 33268817, 2021).
metastatic prostate carcinoma (1 paper, 2018). A carcinoma that arises from the prostate gland and has spread to other anatomic sites. "Ten women with metastatic breast cancer and 10 men with metastatic prostate cancer were treated with 2.5 mg p.o. for 24 h, which led to a normalization of prolactin levels in all patients." (PMID 30349477, 2018). "A clinical phase 2 trial with progressive metastatic prostate cancer revealed that prolactin was suppressed in 10 of 11 patients without serious side effects upon treatment with 3 × 2.5 mg/day bromocriptine." (PMID 30349477, 2018).
Morvan syndrome (1 paper, 2024). Morvan syndrome is a rare, life-threatening, acquired neurologic disease characterized by neuromyotonia, dysautonomia and encephalopathy with severe insomnia. "Factors including platelets, prolactin, and immune-inflammatory elements may contribute to the complexity of the hypercoagulable state in Morvan’s syndrome." (PMID 39029039, 2024).
mycotoxicosis (1 paper, 2020). Poisoning caused by the ingestion of mycotoxins (toxins of fungal origin). "Prolactin homeostatic levels are sensitive to tall fescue toxins and are a measure of the degree of tall fescue mycotoxicosis." (PMID 33173791, 2020).
myelitis (1 paper, 2025). An inflammatory process affecting the spinal cord. "Elevated PRL levels during MS and NMO attacks, particularly the more pronounced elevations observed during myelitis episodes, suggest a potential immunomodulatory role for PRL in the pathogenesis of autoimmune demyelinating diseases." (PMID 41476991, 2025).
myopia (1 paper, 2024). "A study found no abnormal serum levels of certain stress mediators, including cortisol, Adrenocorticotropic Hormone, growth hormone, and prolactin, in myopia." (PMID 39061766, 2024).
myositis (1 paper, 2024). "Comprehensive myositis laboratory profile including ENA JO-1 AB, aldolase, and ANA, with normal prolactin levels drawn immediately post-seizure." (PMID 38813074, 2024).